ENSG00000283175 (novel transcript, antisense to MASP1)
Synonyms: LOC101929130
Gene: Long non-coding RNA gene on chromosome 3 (187,291,238 to 187,297,940, forward strand). Ensembl gene ENSG00000283175.
Gene Ontology:
Biological process: SRP-dependent cotranslational protein targeting to membrane, signal sequence recognition
Cellular component: signal recognition particle, endoplasmic reticulum targeting